BAP1 (BRCA1 associated deubiquitinase 1)
Diseases named in the same sentence as BAP1 in open-access papers (continued):
Sharing a sentence is not in itself a finding about the gene and the disease.
mesothelioma (continued). "However, it is critical to probe genes beyond BAP1 that confer differential susceptibility to mesothelioma development and treatment response." (PMID 30060501, 2018). "Interestingly, our results suggest that mesothelioma cells expressing wild-type BAP1 are more aggressive, which is consistent with clinical studies associating BAP1 expression with worse prognosis in mesothelioma." (PMID 29069806, 2017). "Loss of one BAP1 allele either inherited or acquired during life has been associated with environmental stress-induced carcinogenesis, like UV light for uveal melanoma and asbestos for mesothelioma." (PMID 31225437, 2017). "Most recently, the tumor suppressor BAP1 has been identified as the causal gene in a tumor predisposition syndrome including, among others, atypical Spitz tumors, cutaneous and uveal melanoma, mesothelioma, and clear cell renal carcinoma." (PMID 28283772, 2017). "Interestingly, in mesothelioma, BAP1 inactivation is associated with less aggressive tumors and a better outcome." (PMID 29069806, 2017). "BAP1 has a high somatic mutation rate in uveal melanoma and mesothelioma but very few mutations in lung cancer, suggesting that another regulation pathway may be involved in the dysregulation of BAP1 in lung cancer." (PMID 26885612, 2016). "Moreover carriers of germline BAP1 mutations are at increased risk of mesothelioma when exposed to asbestos, including low doses that usually are not sufficient to cause cancer." (PMID 28191281, 2016). "We found BAP1 mutations in 40% of families with CM and mesothelioma." (PMID 25803691, 2015). "In addition to mesothelioma, germline BAP1 mutations confer increased susceptibility for the development of several other tumors including uveal melanoma, cutaneous melanoma, renal cell cancers and possibly other cancers." (PMID 26202904, 2015). "Germline BAP1 mutations cause a cancer syndrome characterized by high incidence of mesothelioma (MM), uveal melanoma and other cancers, and by very high penetrance, as all individuals carrying BAP1 mutations developed at least one, and usually several, malignancies throughout their lives." (PMID 26683624, 2015). "Interestingly, FOXK1 has been reported to interact with BAP1, which was recently found to be mutated in mesothelioma." (PMID 23626673, 2013). "Summary of the patient samples collected indicating our in-house ID, whether it was subsequently confirmed as mesothelioma, histological subtype, BRCA1-associated protein 1 (BAP1) status, whether the sample has been assessed for implantation (CAM-PDX), and which figures the samples appear in." (PMID 40568242, 2025). "In hereditary cases (BAP1 tumor predisposition syndrome), germline BAP1 mutations significantly increase susceptibility: affected individuals may present with mesothelioma at younger ages, even with minimal asbestos exposure, and their tumors tend to be less aggressive, with more prolonged survival." (PMID 41375066, 2025). "Primary meningeal melanocytic tumors can also occur in patients with the BAP1 tumor predisposition syndrome (germline BAP1 mutation) that confers a higher risk of meningeal, uveal, and cutaneous melanomas, as well as other tumor types, including mesotheliomas and clear cell renal cancers." (PMID 39061148, 2024). "In contrast to the situation observed in mesothelioma and renal clear cell carcinoma (ccRCC), where BAP1 function is commonly affected by mutations, in pancreatic cancer, approximately 26% of patients exhibit low expression of BAP1 due to copy number deletions." (PMID 39350280, 2024). "BAP1 mutations promote development of cancer across multiple tissue types and are associated with differential survival outcomes, for example worse outcomes in uveal melanoma, kidney renal clear cell carcinoma and hepatocellular carcinoma, but improved outcomes in mesothelioma." (PMID 39554490, 2024).
mesothelioma (continued). "In addition to predisposing to RCC, germline BAP1 mutations predispose to mesothelioma (pleural and peritoneal), uveal melanoma and cutaneous melanoma, so the personal or family history of these features should lead to the suspicion of BAP1 tumour predisposition syndrome (BPTS)." (PMID 38802529, 2024). "Recent reports have suggested that individuals inheriting a loss-of-function mutation in breast-cancer (BRCA) 1-associated protein 1 (BAP1) may suffer from several malignancies, mostly uveal melanoma, mesothelioma, clear-cell renal cancer and rhabdoid meningioma." (PMID 36641486, 2023). "However, there is some evidence to suggest that mesothelioma occurring as a result of a BAP1 GPV, may be associated with better survival compared to population-based cases." (PMID 37607989, 2023). "Furthermore, studies should be undertaken to explore whether BAP1 loss exhibits interactions with other genetic or epigenetic changes that affect mitotic progression in mesothelioma." (PMID 36550359, 2023). "Therefore, simultaneous targeting of these two crucial pathways (PRC2 inhibition plus mevalonate pathway inhibition) might be an attractive strategy for treating BAP1-deficient mesothelioma." (PMID 36657447, 2023). "have shown that loss of Bap1 is directly linked to elevated expression of mevalonate pathway genes in mouse liver, we checked whether this pathway is associated with disease outcome in mesothelioma." (PMID 36657447, 2023). "Besides, carriers of the heterozygous germline BAP1 mutation can be affected by any cancer type, but they are mostly susceptible to asbestos carcinogenesis and develop mesotheliomas, a “preference” suggested to be attributed to the higher amounts of HMGB1 secreted by these mutant cells." (PMID 35326567, 2022). "BAP1 loss may also progress to malignant mesothelioma in situ and then to invasive mesothelioma." (PMID 35950141, 2022). "BAP1 is an important regulator of interactions between genes and the environment, and loss of BAP1 enhances the susceptibility of fibroblasts and mesothelial cells to ionising or UV irradiation, and to asbestos, which contributes to the development of asbestos-induced mesothelioma in vivo." (PMID 34226685, 2021). "However, given the association of hereditary predisposition syndromes in patients with melanoma and/or mesothelioma with renal neoplasia, universal screening may be warranted in this patient population with a panel that includes BAP1, MITF, and FLCN." (PMID 34767027, 2021). "In addition to CM, the tumor spectrum of BAP1 pathogenic variants includes uveal melanoma (UM), mesothelioma, basal cell carcinoma (BCC), renal cell carcinoma (RCC), and BAP1-inactivated melanocytic tumors (BIMTs), which together constitute the BAP1-tumor predisposition syndrome (BAP1-TPDS)." (PMID 32325837, 2020). "However, as both sporadic and familial MPM has a high prevalence of inactivating BAP1 mutations, this epigenetic axis may be critical to mesothelioma carcinogenesis." (PMID 30060501, 2018). "Based on our experience we strongly recommend that mesothelioma occurring at a young age (< 50 years old), or in patients with multiple family members affected by mesothelioma or other cancers associated with germline BAP1 mutations should be tested for BAP1 gene mutations." (PMID 30001711, 2018). "Although loss of BAP1 expression in cytology could be applied to support mesothelioma diagnosis, histological specimens still have the added advantage, which is associated with the better diagnostic performance of histological diagnostic criteria when compared with cytological one." (PMID 28978163, 2017). "Interestingly, somatic BAP1 mutation is reported to be more common in current or ex-smokers who develop mesothelioma and could conceivably compound HDAC2 instability in response to cigarette smoke." (PMID 25970771, 2015).
mesothelioma (continued). "The mesothelioma patient derived tumor xenografts with mutational alterations that mimic those observed in patient tumors which we established can be used for preclinical development of novel drug regimens and for studying the functional aspects of BAP1 biology in mesothelioma." (PMID 25952750, 2015). "In mesothelioma pathogenesis, BAP1 dysfunction contributes to altered cellular growth, enhanced survival, and resistance to apoptosis." (PMID 40016284, 2025). "BAP1-TPDS calls for annual dermatologic and ophthalmologic assessment and awareness of mesothelioma risk." (PMID 41440226, 2025). "Using multiple statistical approaches, our results did not detect a significant difference between the probabilities of mesothelioma occurrence in Bap1-mutant and WT mice." (PMID 40867321, 2025). "We report unique clinicopathologic and genomic features that distinguish TM from other mesotheliomas, including a lower frequency of BAP1 alterations." (PMID 40739067, 2025). "Yet, when they are exposed to even trace amounts of asbestos fibers, Bap1-mutant mice develop a high incidence of mesothelioma." (PMID 40867321, 2025). "We then used a rigorous set of Bayesian statistical analyses to interrogate the incidence of spontaneous mesotheliomas in Bap1-mutant versus WT mice in various genetic backgrounds." (PMID 40867321, 2025). "To identify molecular features associated with this sensitivity, we examined the mutational status of genes commonly altered in mesothelioma, including NF2, LATS1/2, and BAP1." (PMID 41463232, 2025). "Using the exact binomial test, the observed rates of mesothelioma and their 95% confidence intervals in the Bap1-mutant and WT groups were 0.006 [0.0007, 0.022] and 0 [0.00, 0.016], respectively." (PMID 40867321, 2025). "By reapplying their Bayesian evaluation of our base data with their HCD, the posterior probability of a difference in the rates of mesothelioma occurrence between Bap1- mutant mice and WT mice increased to >99.9%." (PMID 40867321, 2025). "Recently, Nielsen and colleagues performed a Bayesian analysis to reexamine the data from our 2016 report to determine if the rate of spontaneous mesotheliomas among germline Bap1 heterozygous mice is greater than among WT mice." (PMID 40867321, 2025). "Approximately 65% of mesothelioma cases involve the inactivation of BAP1, a tumor suppressor gene located on chromosome 3p21.1." (PMID 40362535, 2025). "BAP1 staining is a routine procedure for patients with mesothelioma and has been extensively studied as a tumour suppressor in this context." (PMID 39939955, 2025). "BAP1-TPDS—germline BAP1 mutations confer an elevated risk of clear-cell RCC—albeit less frequently—alongside uveal melanoma and mesothelioma; 2023 European guidance outlines surveillance for carriers." (PMID 41440226, 2025). "Three mesothelioma cell lines were used in this assay: NCI-H2052 cells harboring NF2 mutations, Y-MESO-27 cells with LATS1/2 alterations, and NCI-H2452 cells carrying BAP1 mutations." (PMID 41463232, 2025). "Mesothelioma is characterized by the inactivation of tumor suppressor genes, with frequent mutations in neurofibromin 2 (NF2), BRCA1-associated protein 1 (BAP1), and cyclin-dependent kinase inhibitor 2A (CDKN2A)." (PMID 40362535, 2025). "Genomic studies have revealed that mesothelioma is predominantly characterized by loss-of-function alterations in tumor suppressor genes, with mutations in CDKN2A, BAP1, and NF2 being the most frequently observed." (PMID 41463232, 2025). "The analysis determined that BAP1 mutant cells were significantly less sensitive than BAP1 wild-type cell lines to gemcitabine, and silencing of BAP1 significantly increased resistance of mesothelioma cells to gemcitabine." (PMID 40361508, 2025).
mesothelioma (continued). "Given its key role in tumor suppression, BAP1 has emerged as a potential biomarker for diagnosis, prognosis, and therapeutic targeting in mesothelioma, making it an essential component in understanding the molecular landscape of PM." (PMID 40016284, 2025). "Transcriptomic analyses from The Cancer Genome Atlas (TCGA) showed that BAP1 mRNA expression in mesotheliomas inversely correlates with a type I IFN gene signature." (PMID 41463268, 2025). "Research studies conducted by Napolitano and Xu found that BAP1 heterozygous rats had double the incidence and a faster progression of mesothelioma compared to wild-type BAP1 homozygous rats, considering environmental influences." (PMID 40506895, 2025). "We then examined the posterior distributions of the OR, RR, and RD to compare the occurrence of mesothelioma between Bap1-mutant and WT mice." (PMID 40867321, 2025). "Spontaneous mesotheliomas were found in 2 of 93 Bap1-mutant mice and 0 of 43 wild-type (WT) littermates at publication." (PMID 40867321, 2025). "A retrospective review of 229 mesothelioma patients aimed to determine the clinicopathological significance of BAP1 IHC in mesothelioma." (PMID 40361508, 2025). "The chemosensitivity of gemcitabine on human mesothelioma cell lines carrying BAP1 wild-type versus mutant cells was evaluated in a preclinical study." (PMID 40361508, 2025). "UM is one core tumor in dominantly inherited BAP1 tumor predisposition syndrome (BAP1‐TPDS, OMIM 614327), along with mesothelioma, cutaneous melanoma, and clear cell renal cell carcinoma." (PMID 39344744, 2025). "Despite using the most conservative prior, we still did not detect a significant difference between the probabilities of mesothelioma occurrence in Bap1-mutant (Pm) and WT (Pw) mice." (PMID 40867321, 2025). "Two mesotheliomas (one in a Bap1+/− mouse; the second in a Bap1+/W mouse) were found in 93 mice from these three Bap1-mutant mouse models." (PMID 40867321, 2025). "A phase II clinical trial has yielded promising results for tazemetostat, an EZH2 inhibitor, in mesothelioma patients with BAP1 inactivation, offering hope for targeted therapies in this patient subgroup." (PMID 40362535, 2025). "We monitored 236 new germline Bap1 heterozygous mice, in several different backgrounds, over their lifetime for the development of spontaneous mesothelioma." (PMID 40867321, 2025). "To determine if the incidence of mesotheliomas in Bap1-mutant mice is significantly increased compared to WT mice, we performed statistical analyses using frequentist and Bayesian frameworks." (PMID 40867321, 2025). "We also backcrossed our heterozygous Bap1+/− knockout mice to 129/Sv or C57BL/6 mice to assess spontaneous mesothelioma formation in these mouse strains." (PMID 40867321, 2025). "BAP1 mediates the poly-deubiquitination of OGT to prevent its proteasomal degradation in NCI-H226 mesothelioma cells." (PMID 39715739, 2024). "Genetic alterations in mesothelioma commonly include BAP1, CDKN2A, and moesin-ezrin-radixin-like tumor suppressors, which play important roles in mesothelioma development." (PMID 39006698, 2024). "Expansion of myeloid cells in the spleen through the process of extramedullary hematopoiesis resulting in splenomegaly has been observed in BAP1 (a core mesothelioma gene) knockout mice." (PMID 39516360, 2024). "Loss of BAP1 and MTAP can support the diagnosis of mesothelioma versus benign mesothelial proliferation: however, morphology (with an invasive pattern) is still the essential tool to distinguish malignant from benign disease." (PMID 39030439, 2024). "BAP1-TPDS is characterized by increased risk of solid tumors, including mesothelioma, cutaneous and uveal melanoma, renal cell carcinoma, and BAP1-inactivated melanocytic tumors." (PMID 38824259, 2024).
mesothelioma (continued). "Loss of the BAP1 protein, despite the absence of alterations in the BAP1 gene and its transcript, has previously been reported in mesotheliomas and other BAP1-related neoplasms, including clear cell renal carcinoma and uveal melanoma." (PMID 39091916, 2024). "First, we used our human mesothelioma cell line panel to validate the BAP1-status-specific efficacy of the drug combination on cell survival." (PMID 38519707, 2024). "Taken together, we were able to show that a combination of FGFR and EZH2 inhibitors is a potentially promising therapeutic strategy for the treatment of BAP1-mutant mesothelioma cells." (PMID 38054839, 2024). "Another study on twelve mesothelioma cell lines indicated that cells harboring NF2 and/or LATS2 mutations were more sensitive to statins than those harboring BAP1 mutations." (PMID 38879686, 2024). "One study further showed that EZH2 inhibition resulted in reduced tumor size in mice with BAP1-inactivated mesotheliomas compared to wild-type mesotheliomas, providing evidence for the potential role of BAP1 in mediating tumor sensitivity to EZH2 inhibition." (PMID 38610930, 2024). "Previously in our lab, we derived cell lines from our autochthonous mesothelioma mouse model with genetically defined BNC (Bap1−/−, Nf2−/−, Cdkn2ab−/−) or NC (Nf2−/−, Cdkn2ab−/−) background." (PMID 38519707, 2024). "Here, we observe that EZH2 inhibitors dramatically enhance the efficacy of FGFR inhibition, sensitising BAP1-mutant mesothelioma and uveal melanoma cells." (PMID 38054839, 2024). "The BRCA1-associated protein-1 (BAP1) is a tumor suppressor gene, whose somatic or germline mutation predisposes patients or families to cancers including uveal melanoma, mesothelioma, renal cell carcinoma and melanoma." (PMID 38473375, 2024). "While NSCLC is characterised by activating mutations in oncogenes, mesothelioma on the other hand is characterised by the frequent inactivating alteration of the CDKN2A, NF2 and BAP1 tumour-suppressor genes." (PMID 38015374, 2023). "Here we report novel functions for BAP1 in mitotic progression highlighting the relationship between BAP1 and control of genome stability in mesothelioma cells with therapeutic implications." (PMID 36550359, 2023). "We recently described new mouse models of mesothelioma where Bap1 deletion accompanied with alterations in genetic drivers Nf2 and Cdkn2ab results in fast and aggressive mesothelioma." (PMID 36657447, 2023). "In mesothelioma, BAP1 loss promotes EZH2 expression, but the opposite association was seen in our data (i.e., BAP1 loss was significantly associated with <80% EZH2 expression)." (PMID 37190202, 2023). "Initial studies showed that BAP1 is deleted or mutated in various human cancer cells and that reexpression of BAP1 in H226 human mesothelioma cells, which lack intrinsic BAP1 expression, reverses their tumorigenicity." (PMID 36754982, 2023). "BAP1 and BRCA1 are encoded by tumour suppressor genes that are frequently lost in human cancers, with BAP1 the most commonly mutated gene in mesothelioma." (PMID 36550359, 2023). "Human BAP1 is a 729 amino acid predominantly nuclear deubiquitinase (DUB), encoded on chromosome 3p21.1, and its inactivation occurs in upwards of 65% of mesotheliomas primarily through somatic mutation and copy number loss." (PMID 36550359, 2023). "Conditional knockout mice targeting Nf2, Bap1, and/or Cdkn2a in cells of the mesothelium exhibited an increased incidence of mesothelioma, and noticeably, the triple-knockout mice showed highly invasive tumors with the shortest survival times." (PMID 37180489, 2023). "We extended this observation to human mesothelioma cell lines and observed that BAP1 mutant human cell lines are more sensitive to ZA treatment than BAP1 WT human cell lines." (PMID 36657447, 2023). "BAP1 expression was detected only in the parental MeT-5A, parental HOMC-D4, and human mesothelioma Y-MESO12 cell lines (BAP1+/+)." (PMID 37479714, 2023).